KIF1B (kinesin family member 1B)
Diseases named in the same sentence as KIF1B in open-access papers (continued):
Sharing a sentence is not in itself a finding about the gene and the disease.
asthma (1 paper, 2025). "This study investigated the role of KIF1B in asthma, particularly focusing on the mechanisms underlying inflammatory responses and pyroptosis regulation, utilising both in vitro and in vivo experimental models." (PMID 41384344, 2025). "The inverse regulation of IL‐10 levels observed in our study further confirmed that pyroptosis was effectively inhibited and asthma‐associated lung injury was protected upon KIF1B silencing." (PMID 41384344, 2025). "Moreover, the results from this study also indicated that KIF1B regulates asthma‐associated pyroptosis, defined as a form of programmed cell death characterised by inflammatory responses." (PMID 41384344, 2025). "Pulmonary function analysis revealed that OVA‐induced asthma significantly increased airway resistance and decreased lung compliance compared to controls, while KIF1B knockdown effectively restored both parameters towards normal values." (PMID 41384344, 2025). "In conclusion, this study elucidates the critical role of KIF1B in asthma pathogenesis and establishes its potential as a novel therapeutic target." (PMID 41384344, 2025). "This investigation demonstrates that KIF1B inhibition represents a promising therapeutic approach for attenuating asthma development through the suppression of inflammatory progression." (PMID 41384344, 2025). "Results showed that KIF1B expression was markedly elevated in bronchial biopsies from asthma patients, OVA‐challenged mouse lungs and IL‐13–stimulated BEAS‐2B cells." (PMID 41384344, 2025). "These mechanistic insights provide evidence supporting the development of KIF1B‐targeted therapies as innovative therapeutic interventions for asthma management." (PMID 41384344, 2025). "In conclusion, these findings identify KIF1B as a key regulator of airway inflammation and pyroptosis in asthma via NLRP3‐dependent signalling." (PMID 41384344, 2025). "Our initial analysis of human asthma cohort datasets indicated significant upregulation of KIF1B in bronchial biopsies from asthmatic patients compared to healthy controls, suggesting a potential role in asthma pathogenesis." (PMID 41384344, 2025). "Collectively, these results demonstrate that both transcript and protein levels of KIF1B are upregulated across multiple experimental models of asthmatic inflammation, suggesting a potential role for KIF1B in asthma pathogenesis." (PMID 41384344, 2025). "Third, our study primarily focused on the acute inflammatory phase, while chronic asthma involves sustained airway remodelling and structural changes that may be differentially regulated by KIF1B." (PMID 41384344, 2025). "Additionally, NLRP3 overexpression experiments were conducted to elucidate the molecular mechanism by which KIF1B mediates inflammatory pathways in asthma pathogenesis." (PMID 41384344, 2025). "While we have demonstrated that KIF1B represents a promising novel therapeutic target for asthma treatment through its effective prevention of oxidative stress and inflammation‐mediated pyroptosis/lung injury, the study has several limitations that warrant consideration." (PMID 41384344, 2025). "Targeting KIF1B may therefore represent a promising therapeutic strategy for controlling asthma progression." (PMID 41384344, 2025). "Therefore, the objective of this study was to investigate the specific role of KIF1B in asthma progression and determine whether it regulates inflammation and pyroptosis in asthmatic responses." (PMID 41384344, 2025). "Our findings demonstrate that KIF1B plays a crucial role in promoting asthmatic inflammation through NLRP3‐mediated pyroptosis, identifying KIF1B as a novel therapeutic target for asthma intervention." (PMID 41384344, 2025). "The present study explored the role of KIF1B (kinesin family member 1B) in asthma pathogenesis using integrated approaches involving human cohort datasets, in vitro airway epithelial cell models and an in vivo ovalbumin (OVA)‐induced asthma mouse model." (PMID 41384344, 2025).
bone metastasis (1 paper, 2025). Transfer of a neoplasm from its primary site to bones. "In this paper, we present a case that initially presented with FUO, and was ultimately diagnosed with HNPGLs with multiple metastases, accompanied by special imaging findings of bone metastasis, an SDHB pathogenic variant, and a KIF1B variant of uncertain significance." (PMID 40917352, 2025).
embryonic carcinoma (1 paper, 2013). "To further test whether Gaa, Isl1, Kif1b, Mtmr2, Pcsk1n, and Snca, are regulated by Pax6, we performed co-transfection studies in cultured P19 embryonic carcinoma and αTN4-1 lens epithelial cells." (PMID 23342162, 2013).
endometrial cancer (1 paper, 2025). Primary or metastatic malignant neoplasm involving the endometrium (mucous membrane that lines the endometrial cavity). "Consistent with our findings of KIF1B's inflammatory regulatory role, a previous study demonstrated that KIF5B, a kinesin family member closely related to KIF1B, regulates epithelial–mesenchymal transition through the PI3K/AKT/mTOR inflammatory pathway in endometrial cancer." (PMID 41384344, 2025).
Hepatitis (1 paper, 2012). Inflammation of the liver. "This study aims to investigate the significance of KIF1B genetic variations in HBV-associated hepatitis in patients of Saudi Arabian ethnicity." (PMID 23028799, 2012).
Insulin resistance (1 paper, 2009). Increased resistance towards insulin, that is, diminished effectiveness of insulin in reducing blood glucose levels. "Furthermore, several potentially important genes regarding the underlying causes of insulin resistance and type 2 diabetes (for example KIF1B and GDF8) have been identified and shown to have different gene expression levels in healthy first degree relatives compared to controls." (PMID 19668377, 2009).
metastatic disease (1 paper, 2015). "The loss of the chromosome arm 1p in six patients with metastatic disease (GIST_124, _131,_178,_150, _174, _188) led also to one copy deletion of KIF1B and of the tumor suppressor ARID1A, a known SWI/SNF chromatin remodeling gene." (PMID 26544626, 2015).
osteosarcoma (1 paper, 2017). A usually aggressive malignant bone-forming mesenchymal neoplasm, predominantly affecting adolescents and young adults. "KIF1B is responsible for intracellular vesicular transport, a process involved in the production matrix in osteosarcoma." (PMID 29113313, 2017).
pulmonary oedema (1 paper, 2025). "OVA treatment increased the lung tissue wet/dry (W/D) ratio, indicative of pulmonary oedema, which was significantly reduced by KIF1B knockdown." (PMID 41384344, 2025).
sarcoidosis (1 paper, 2022). Sarcoidosis is a multisystemic disorder of unknown cause characterized by the formation of immune granulomas in involved organs. "Some dysregulated genes discovered in our meta-analysis have not been found to be associated with sarcoidosis previously, but variations of these genes such as CCNB1, BLOC1S1, and KIF1B are associated to some extent with fibrotic diseases, including complication of sarcoidosis and tuberculosis." (PMID 36203777, 2022).
Sensory axonal neuropathy (1 paper, 2006). An axonal neuropathy of peripheral sensory nerves. "Furthermore, a mutation in the antegrade axonal transport kinesin gene, KIF1B, has been described in a single family with Charcot-Marie-Tooth disease-2A1, a hereditary motor and sensory axonal neuropathy (OMIM 118210)." (PMID 17166276, 2006).
Shock (1 paper, 2022). The state in which profound and widespread reduction of effective tissue perfusion leads first to reversible, and then if prolonged, to irreversible cellular injury. "UPP1, S100A9, KIF1B, S100A12, SLC26A8 emerge remarkable diagnostic performance in pediatric septic shock and involved in immune cells infiltration." (PMID 36439140, 2022).
tumor (31 papers, 2005 to 2025). "DNA isolated from both the patient’s PCC tumor and hPheo1 cell line derived from it was further analyzed by targeted next generation sequencing and Sanger sequenced and determined to harbor a KIF1B variant T827I, considered by PolyPhen-2 to be likely benign." (PMID 36440216, 2022). "A mutation in the KIF1B tumour suppressor was detected (WES) only after chemotherapy in patient CB1008, which was confirmed by targeted ultra-deep sequencing, suggesting that this mutation occurred de novo during therapy." (PMID 34815394, 2021). "These primitive tumours initiate under conditions that impair sympathetic neuroblast culling during development, reported to depend upon either loss of the KIF1B gene associated with chromosome 1p36-deletion, germline KIF1B mutations or Nmyc amplification." (PMID 31805994, 2019). "A small proportion of PPGLs show additional kinase signaling pathway–associated mutations inFGFR1,KIF1B, andMET but these still need to be validated.KIF1B is a tumor suppressor gene necessary for the neuronal apoptosis." (PMID 30345003, 2018). "Assuming that KIF1B is a tumour suppressor, the T827I variant’s pathogenicity for hPheo1 appears uncertain since Sanger sequencing of cDNA with an amplicon spanning exons 23−25 showed that mutant and wildtype alleles are both expressed, and thereby that the wildtype allele is retained." (PMID 33138083, 2020). "It has been reported that loss of the KIF1B-β isoform can enable tumor cells to evade apoptosis, suggesting that in the context of OM, dysfunction of KIF1B may impair the response of local immune and bone cells to infection, thereby promoting infection spread and bone destruction." (PMID 41050653, 2025). "Kinesin family member 1B (KIF1B) is a tumor suppressor gene, and many studies have found that KIF1Bβ can induce cell apoptosis in NB, and NB patients with poor prognosis are usually accompanied by deletion of chromosome 1p36, where KIF1B was located." (PMID 35535346, 2022). "We examined the relationship between ASE and SCNAs for two genes, IP6K2 and KIF1B, which have been previously identified as potential tumor suppressors located within the chromosome 3p and 1p deletion regions." (PMID 35246212, 2022). "Their analysis of different candidate 1p36 tumor suppressor genes, such as Arid1a, Chd5, Camta1, and Kif1b, identified Arid1a as the gene with strongest correlation between expression levels and time to tumor onset." (PMID 34885007, 2021). "While the KIF1B mutation is most likely benign, the NRAS mutation is a known oncogenic variant in other neoplastic diseases, and a novel finding for PPGL tumours, for which reason it became the focus of the present study." (PMID 33138083, 2020). "The gene product of KIF1B is a postulated tumour suppressor with a role in an apoptotic pathway induced by neurotrophin deprivation." (PMID 33138083, 2020). "KIF1B has been shown to act as a tumor suppressor in multiple cancers by acting on various inhibitors of cell proliferation and activators of apoptosis." (PMID 29113313, 2017). "As confirmation, KIF1Bα and KIF1Bβ, two isoforms of the KIF1B gene, have been proposed to have tumor inhibiting effects." (PMID 23634229, 2013). "Lower expression in cell lines was seen in KIF1B and equal levels of cell lines and stage 2 primary tumours in UBE4B, PGD and PEX14." (PMID 15740626, 2005). "In addition, KIF1B is found to be a tumor suppressor gene, which has a potential role in mitochondrial morphological changes." (PMID 35045818, 2022). "KIF1B positively regulates the expression of MT1‐MMP (membrane type 1‐matrix metalloproteinase), which promotes tumor metastasis by affecting processes such as extracellular matrix remodeling and angiogenesis." (PMID 39964093, 2025). "For example, chromosome 1p deletions affect many potential tumor suppressors including CHD5, CAMTA1, KIF1B, CASZ1, UBE4B, and MIR34A." (PMID 35246212, 2022).
tumor (continued). "At least five genes located at 1p36 (CHD5, CAMTA1, KIF1B, CASZ1, and MIR34A) were already suggested to be tumor suppressors." (PMID 34956867, 2021). "The tumour suppressor DLC2 and Kif1B are thus central components of a signalling network that guides spindle positioning, cell–cell adhesion and mitotic fidelity." (PMID 25518808, 2014). "Among the MNA tumors (n=10), five tumor suppressor genes (among other genes) were underexpressed within the distal 1p: CAMTA1, KIF1B, PRDM2, FABP3, and CDKN2C; whereas MYCNOS and MYCN were the two top differentially upregulated genes on 2p." (PMID 23656755, 2013). "Upregulated genes were primarily associated with cell adhesion/invasion/metastasis (ELMO2, ADAM9, DLG1, TRPM7), metabolism/mitochondrial function (FAM120A, DARS2), and cellular transport/axonal trafficking (KIF1B, TBC1D5), indicating the presence of tumor microenvironment stress." (PMID 41404060, 2025). "Several other putative tumor suppressors in the chromosome 1p or 11q deletion regions including CHD5, UBE4B, CADM1, and ATM, have patterns that are similar to KIF1B, where a subset of samples exhibit strong ASE in the absence of deletions." (PMID 35246212, 2022). "Of import, our data indicated a tumour suppressive role for AS events in CD47 (ES) and KIF1B (AT)." (PMID 32939931, 2020). "Here we demonstrate that the tumour suppressor DLC2, a negative regulator of Cdc42, and the interacting kinesin Kif1B coordinate cell junction maintenance and planar spindle positioning by regulating microtubule growth and crosstalk with the actin cytoskeleton." (PMID 25518808, 2014). "Hence, the tumour suppressor DLC2 and the kinesin Kif1B are required for chromosome stability." (PMID 25518808, 2014). "Previous studies have identified CHD5 and KIF1B as candidate tumor suppressor genes in this region, and more recently it was reported that disruption of PER3 function may indicate the likelihood of tumor recurrence in patients with ERα-positive tumors." (PMID 25106495, 2014). "The genes UBE4B, KIF1B, PGD, APITD1, DFFA and PEX14 are down-regulated in high stage NB tumours, a feature that can not be explained by CpG island methylation." (PMID 15740626, 2005). "The analyzed fragments of the genes UBE4B, KIF1B, PGD, DFFA and PEX14 were not methylated in the panel of NB primary tumours and cell lines." (PMID 15740626, 2005). "We then analyzed CALU, KIF1B, and POLR3G expression in TCGA database and NPC microarray GSE53819, the results showed that CALU and POLR3G are highly expressed in HNSC tumor tissues while KIF1B is not significant, but all of them are highly expressed in NPC tissues in GSE53819." (PMID 39964093, 2025). "Hence, the six genes UBE4B, KIF1B, PGD, APITD1, DFFA and PEX14 are down-regulated in high stage NB tumours, a feature that can not be explained by methylation, rather by a mechanism still remaining to be discovered." (PMID 15740626, 2005).
cancer (9 papers, 2012 to 2023). A tumor composed of atypical neoplastic, often pleomorphic cells that invade other tissues. "Hereditary PCC accounts for ~35% of cases and has been associated with germline mutations in several cancer susceptibility genes (e.g., KIF1B, SDHB, VHL, SDHD, RET)." (PMID 32354376, 2020). "The KIF1B gene has previously been reported to be differentially expressed in 32 cancer experiments and to be alternatively spliced in heart, muscle and thyroid." (PMID 28545391, 2017). "Kinesin family member 1B (KIF1B) gene resides in the chromosomal region 1p36.22 and has been reported to have frequent deletions in a variety of human cancers." (PMID 23028799, 2012). "Interestingly, our panel included genes already described to be cancer predisposition genes (FAS, ITK, KIF1B, PGR and MET) or previously reported as playing important roles in cancer (ABI1, ARID5B, DNMT3A, HEY1, KDM5C, NCOA1, NUP98, and SLC34A2), or in DNA repair process (FANCF)." (PMID 30925779, 2019). "Several of these genes are related to cancer, including CD44, DST, GLS, GNAS, KIF1B and AHRR." (PMID 34086943, 2021).
peripheral neuropathy (5 papers, 2014 to 2023). A disorder affecting the peripheral nervous system. "The fact that a mutation in the motor protein Kif1b can underlie a peripheral neuropathy led to the conclusion that KIF1B is the long sought after CMT2A gene." (PMID 24705285, 2014). "Additionally, a single loss of function variant in KIF1B has been described in a family with peripheral neuropathy (CMT2A1), and heterozygous KIF1B −/+ mice exhibit chronic peripheral neuropathy and impaired synaptic vesicle transport." (PMID 33810506, 2021). "KIF1B mutations result in non-demyelinating peripheral neuropathy, indicating that KIF1B is essential for neuronal function." (PMID 33447134, 2020). "Three of the 4 other peripheral neuropathy-related genes (PMP22, KIF1B, GLA) also have shown to contribute to aberrant mitochondrial dynamics, axonal transport, and/or mitophagy." (PMID 37234784, 2023).
infection (4 papers, 2015 to 2025). The state of being infected such as from the introduction of a foreign agent such as serum, vaccine, antigenic substance or organism. "To test whether BORC-related lysosome trafficking components mediate BCV trafficking during infection, we analyzed the dynamics of the interaction of BCVs with LAMTOR1 (a central component of mTORC1), the small GTPase ARL8b, and kinesin KIF1b and KIF5b proteins during infection." (PMID 35587649, 2022). "Besides the cleavage of proteins involved in nucleocytoplasmic transport we also observed GP63-dependent mislocalization of proteins such as Kif1B after infection by L. mexicana and L. major WT but not after infection by L. major GP63-/-." (PMID 25826301, 2015).
neurological disorder (3 papers, 2013 to 2026). "The interacting clone contained KIF1B cDNA sequence, initially suggesting that it was KIF1B, a kinesin molecular motor protein previously mutated in a pedigree with neurological disease." (PMID 24244371, 2013). "Mutations in KIF1A (resulting in KIF1-associated neurological disorder/KAND), KIF1B (resulting in Charcot-Marie-Tooth disease), KIF5A (resulting in ALS), and KIF21B (causing neurodevelopmental disorders) result in various neurological disorders where intracellular transport defects are evident." (PMID 41277110, 2026).
cardiovascular diseases (1 paper, 2024). "In terms of potential therapeutic strategies for cardiovascular diseases, inhibition of hsa-ABLIM1_0001, hsa-RNF13_0004, and hsa-KIF1B_0001, or overexpression of hsa-MYOM1_0001, hsa-AC096949_0001, and hsa-PDLIM5_0001, may be promising in promoting cardiomyocyte cell cycle and heart regeneration." (PMID 38916964, 2024).
neurodegenerative disease (1 paper, 2021). A disorder of the central nervous system characterized by gradual and progressive loss of neural tissue and neurologic function. "KIF1B (p = 4.49 × 10−21) expression is significantly increased in AD and is associated with accelerated progression in neurodegenerative diseases." (PMID 33804025, 2021).
psychiatric disorder (1 paper, 2025). A disorder characterized by behavioral and/or psychological abnormalities, often accompanied by physical symptoms. "As a candidate for a crucial Kifs gene that is likely related to microglia polarization, we selected psychiatric disorder-related KIFs (KIF3A, KIF17, KIF1A, KIF1B, and KIF13A)." (PMID 39885501, 2025).